SRR (serine racemase)
Diseases named in the same sentence as SRR in open-access papers (continued):
Sharing a sentence is not in itself a finding about the gene and the disease.
chlamydial infections (1 paper, 2024). "Second, unlike serine dehydratase, datasets in the Human Protein Atlas reveal SRR to be expressed broadly in multiple tissues, including mucosal surfaces associated with chlamydial infections such as the eye and the female reproductive tract." (PMID 38718865, 2024).
chronic renal failure (1 paper, 2022). "In chronic renal failure rats, TFA administration improved renal injury, remodeled gut microbiota dysbiosis, including regulated intestinal-derived metabolites such as D-serine, D-amino acid oxidase, L-serine, and serine racemase, suppressed the levels of pro-inflammation (TNF-α and IL-1β)." (PMID 35123452, 2022).
cognitive decline (1 paper, 2024). "SRR downregulation in the aging rat hippocampus has been shown to play a role in cognitive decline." (PMID 38428408, 2024).
cyst (1 paper, 2021). A sac-like closed membranous structure that may be empty or contain fluid or amorphous material. "We find aging and lifespan-related genes, serine racemase and MsrA, are enriched in the cyst." (PMID 34132809, 2021).
dementia (1 paper, 2021). Loss of intellectual abilities interfering with an individual's social and occupational functions. "In contrast, in AD there appears to be activation of serine racemase, increased levels of D-serine and overstimulation of NMDARs, resulting in cytotoxicity, synaptic deficits, and dementia." (PMID 34707525, 2021).
depression (1 paper, 2013). "The influence of low D-serine levels on depression-like behavior has not been tested so far as serine racemase-deficient mice have not been examined in behavioral paradigms of depression." (PMID 23805296, 2013).
glioma (1 paper, 2010). A benign or malignant brain and spinal cord tumor that arises from glial cells (astrocytes, oligodendrocytes, ependymal cells). "Here we report studies in C6 glioma cells, which “simulate” the forebrain, in that the cells express SRR and ASCT2 but lack DAO activity." (PMID 20091774, 2010). "We have measured SRR and DAO expression and activity, [3H]D-serine uptake, and ASCT2 mRNA expression in C6 glioma cells 48 hr after the addition of serine isomers." (PMID 20091774, 2010).
Hypertension (1 paper, 2024). The presence of chronic increased pressure in the systemic arterial system. "The variable with the lowest p-value is hypertension, while the SNP with the lowest p-value of 0.00826 is rs391300 of the SRR gene." (PMID 39561140, 2024).
injury (1 paper, 2020). Damage inflicted on the body as the direct or indirect result of an external force, with or without disruption of structural continuity. "Accordingly, gut microbiome diversity is significantly damaged in patients with kidney injury, along with the disorder host homeostasis and confusion of its metabolites, including d-amino acid oxidase (DAO), serine racemase (SRR), d-serine, and l-serine." (PMID 33101025, 2020).
methamphetamine dependence (1 paper, 2011). A drug dependence that is a psychological dependency on the regular use of methamphetamine. "The present study revealed that the SRR gene did not affect susceptibility to methamphetamine use disorders, but it was associated with several clinical phenotypes of methamphetamine dependence and psychosis." (PMID 21886585, 2011).
Obesity (1 paper, 2018). Accumulation of substantial excess body fat. "Instead, our screen suggests that different nearby cis gene may be more fruitful for further functional follow up for obesity, namely ZCCHC8, VPS33A, RSRC2; SPDEF, NUDT3; SETD1, VKORC1; SGSM2, SRR; VASP, SIX5; OTX1; BANK1; ARIH1; ELL; CHST8, respectively." (PMID 29608557, 2018).
oral squamous cell carcinoma (1 paper, 2016). "Although no direct evidence has indicated a relationship between SRR and metastasis, NMDA receptors are associated with cell migration and metastasis in oral squamous cell carcinoma." (PMID 26913720, 2016).
substance abuse (1 paper, 2011). The use of a drug for a reason other than which it was intended or in a manner or in quantities other than directed. "Therefore, reduced NMDA receptor signaling due to possession of the C allele of rs408067 of the SRR gene may be a protective factor against a worse prognosis of methamphetamine psychosis and heavy multi-substance abuse behaviors." (PMID 21886585, 2011).
temporal lobe epilepsy (1 paper, 2018). A localization-related (focal) form of epilepsy characterized by recurrent seizures that arise from foci within the temporal lobe, most commonly from its mesial aspect. "In this study, we aimed to investigate the genetic roles of SRR and a neighbouring gene, nonsense‐mediated mRNA decay factor (SMG6), in temporal lobe epilepsy (TLE)." (PMID 29363864, 2018).
cancer (4 papers, 2016 to 2024). A tumor composed of atypical neoplastic, often pleomorphic cells that invade other tissues. "We wondered if the differential expression of SRR was related to the prognosis of patients with different cancer types." (PMID 35923695, 2022). "Serine racemase (SRR) is thought to play a role in the central nervous system, but its role in cancers, particularly in EC, is largely unknown." (PMID 35923695, 2022). "The significant and positive correlations suggested that SRR, like many other tumor suppressor genes, may work together to fight cancer, especially in UCEC." (PMID 35923695, 2022). "Different cancer cell lines had different levels of SRR expression." (PMID 35923695, 2022). "SRR may function as a tumor suppressor gene in some cancers, such as KIRC and UCEC, based on expression and survival analysis." (PMID 35923695, 2022). "By inhibiting these pathways, Rab27B and SRR could be effective and functional downstream targets of miR-193a-3p and miR-193a-5p in the mechanism of cancer metastasis." (PMID 26913720, 2016). "However, little is known about SRR’s role in human cancer, and its role in cancer development and tumor metabolism is unknown." (PMID 35923695, 2022).
neurodegenerative disease (2 papers, 2023). A disorder of the central nervous system characterized by gradual and progressive loss of neural tissue and neurologic function. "Several studies have reported abnormal glial expression of SRR in neurodegenerative diseases associated with neuroinflammation." (PMID 37455930, 2023).
tumor (1 paper, 2022). "As previously stated, SRR is involved in the metabolism of L-serine, and the decrease of L-serine may result in a reduced one-carbon metabolism source, which has been linked to tumor growth." (PMID 35923695, 2022). "This suggested that SRR was important in regulating tumor immunity and, therefore, influenced patient prognoses." (PMID 35923695, 2022). "First, we compared the expression of SRR mRNA in tumor and normal tissues." (PMID 35923695, 2022).
SRR also shares sentences with these, for which no sentence is quoted: diabetic retinopathy (2 papers); Parkinson disease (2); atherosclerosis (1); atopic dermatitis (1); bacteremia (1); cognitive disorder (1); coronary artery disease (1); endometrial carcinoma (1); endothelial dysfunction (1); gestational diabetes (1); infection (1); ischemic stroke (1); neurological diseases (1); psychosis (1).